TNF (tumor necrosis factor)
Diseases named in the same sentence as TNF in open-access papers (continued):
Sharing a sentence is not in itself a finding about the gene and the disease.
psoriatic arthritis (continued). "TNF-alpha is located in the major histocompatibility complex (MHC) region on the chromosome 6p21.3, region that showed the strongest signal of association in the genome-wide association study that included psoriatic arthritis patients." (PMID 21954344, 2011). "In the elderly, psoriatic arthritis is considered to be more severe and to have a less favorable outcome than young-onset psoriatic arthritis, suggesting that there is more frequent use of aggressive or innovative treatments such as anti-TNFα in older patients." (PMID 23509636, 2011). "The purpose of this study was theevaluation of synovial effusion (SE), synovial fluid (SF) and synovial tissue (ST) biomarkers in relation to disease activity indexes to assess the response to intraarticular (IA) tumor necrosis factor (TNF)-α blockers in psoriatic arthritis (PsA)." (PMID 20642840, 2010). "Anti-TNF therapies represent a breakthrough in the treatment of severe psoriatic arthritis." (PMID 19356232, 2009). "Some studies suggest that the tumor necrosis factor alpha component (TNFα) may be considered to be the principal biomarker for PsA diagnosis since treatment with agents that decrease the levels of the TNF are beneficial for psoriatic arthritis patients." (PMID 38475046, 2024). "Consequently, these elevated TNF-α levels may contribute to the pathogenesis of psoriatic arthritis." (PMID 37937010, 2023). "Interestingly, TNF-alpha is a therapeutic target for psoriatic arthritis, perhaps the downstream genes identified by DIME could also be explored as a therapeutic target for psoriatic arthritis." (PMID 34108969, 2021). "Finally, as the indication for TNFα inhibitor treatment was derived from the specialism of the prescriber, we were unable to make distinctions between the individual RD, such as RA, AS, psoriatic arthritis, and juvenile idiopathic arthritis." (PMID 34302442, 2021). "Interestingly, some studies have identified a pattern of earlier discontinuation of anti‐TNF agents in females with psoriatic arthritis, compared to males, attributed to a combination of higher likelihood of reduced response to treatment and adverse drug effects." (PMID 35663775, 2021). "Consequently, we sought to assess whether metabolomic profiles in the urine may have a role in predicting responses to TNF antagonists in patients with RA and psoriatic arthritis (PsA)." (PMID 23460124, 2013). "Currently, regarding TNF-α antagonist therapy for patients with AS or psoriatic arthritis, the French Society for Rheumatology recommendations suggest that there is insufficient evidence for concomitant disease-modifying antirheumatic drugs improving the effectiveness of TNF-α antagonist therapy." (PMID 21639907, 2011). "According to this hypothesis, the paradoxical adverse effects of anti-TNF-alpha treatment, such as the exacerbation of psoriatic skin lesions in patients with psoriatic arthritis receiving anti-TNF-alpha therapy, can be considered as a consequence of the disbalance between the two cytokines." (PMID 21603192, 2011). "Of note, 1 patient with psoriatic arthritis who developed myelitis due to MOGAD (MOG-IgG 1:1,000 by live CBA) was receiving the anti–tumor necrosis factor (TNF)-α agent adalimumab." (PMID 39442039, 2025). "Patients treated with the antibody anti-TNFα infliximab presented a reduction in VEGF expression and improvement of the symptoms of psoriatic arthritis." (PMID 36417626, 2022). "Additionally the European Congress of Rheumatology published the findings of an investigation in 2019 that also found no increased risk of malignancy in patients with psoriatic arthritis treated with anti-TNF therapy in 4 nordic countries (Denmark, Finland, Iceland and Sweden)." (PMID 34648530, 2021). "This is reflected in the fact that biologic agents targeting TNFα are effective in IBD as well as inflammatory arthritides such as RA, axial spondyloarthritis and psoriatic arthritis." (PMID 34745229, 2021).
psoriatic arthritis (continued). "The purpose of the present study was to investigate bone trabeculation in a patient with psoriatic arthritis using UHF MRI and to assess changes related to a TNFα antibodies therapeutic strategy." (PMID 34010320, 2021). "TNF‐α inhibitors such as etanercept, infliximab, and adalimumab have also been approved by the FDA for treatment of moderate to severe psoriasis and psoriatic arthritis." (PMID 32421085, 2020). "TNF-α, RANKL and leptin were positively correlated with Psoriatic Arthritis Joint Activity Index (PsAJAI)." (PMID 23144698, 2012). "TNF is a cytokine involved in the pathophysiology of other chronic inflammatory diseases such as chronic inflammatory bowel disease (IBD), spondylitis, psoriatic arthritis, and intra- and inter-individual variability in response is also observed in these patients." (PMID 40428231, 2025). "In support of the role for chronic inflammation in the impairment of PMN responses, PMNs isolated from patients with the chronic inflammatory condition psoriatic arthritis had diminished ROS production, phagocytosis, NETosis, and MPO release when stimulated with TNF compared to healthy controls." (PMID 40333334, 2025). "Additionally, tumor necrosis factor (TNF) inhibitors are, in his opinion, as efficacious as IL-17 inhibitors for psoriatic arthritis." (PMID 41254515, 2025). "In the EXCEED study, a head-to-head trial, comparing secukinumab (an IL-17 inhibitor) vs. adalimumab (a TNF-α inhibitor) for treatment of active psoriatic arthritis, reported two MACEs in the secukinumab group (n=426) and none in the adalimumab group(n=427)." (PMID 38384460, 2024). "In the phase 3b COSMOS trial, guselkumab demonstrated efficacy in treating participants with active psoriatic arthritis (PsA) and inadequate response (IR; lack of efficacy or intolerance) to tumor necrosis factor inhibitors (TNFi)." (PMID 37587493, 2023). "We used a whole blood based functional flow cytometry assay to characterize immune cells from RA patients (treated or not), healthy donors and psoriatic arthritis (PsA) patients according to their responses to LPS and/or anti-TNFα (infliximab, IFX)." (PMID 35842449, 2022). "We explored whether serum cytokines could be used as biomarkers for optimal use of tumor necrosis factor inhibitors (TNF-i) and interleukin (IL)-17 inhibitors (IL-17-i) in patients with psoriatic arthritis (PsA)." (PMID 35428323, 2022). "However, other studies have revealed that high baseline S100A12 concentration is associated with higher disease activity and response to methotrexate (MTX) and anti-TNF therapy in patients with JIA including pJIA, ERA, oligoarticular and psoriatic arthritis." (PMID 34425842, 2021). "Although biological drugs targeting TNF, IL-17, and IL-12/IL-23 have been approved for the treatment of psoriatic arthritis with destructive spondyloarthritis, there is no way to differentiate the use of these drugs." (PMID 32944095, 2020). "Although some studies report a lower response in obese patients with axial spondyloarthritis, others showed no influence of body mass on anti-TNFα treatment in psoriatic arthritis patients." (PMID 29546695, 2018). "Some evidence demonstrates that p38 activity is neither affected in TNF-transgenic mice nor in patients with psoriatic arthritis (PsA)." (PMID 29276516, 2017). "Increased serum levels of many cytokines were indeed found in other rheumatic diseases: notably psoriatic arthritis (IL-6, IL-7, IL-10, and IFN-γ, TGF-β, or TNF-α) suggesting that such rises may reflect inflammation rather than being disease specific." (PMID 28057980, 2016). "Of note, TNF-α-blocking agents, such as etanercept, induce amelioration of clinical symptoms, laboratory parameters of inflammation, and radiological progression in patients with immune-mediated arthritis, such as RA, JIA, and psoriatic arthritis." (PMID 27123929, 2016).
psoriatic arthritis (continued). "Both TNF antagonists and ustekinumab are approved for psoriatic arthritis, but American College of Rheumatology (ACR) 20 response rates may be somewhat higher for TNF antagonists." (PMID 26058083, 2015). "This study aimed to examine the changes in biomarker levels in responders and non-responders to tumor necrosis factor alpha inhibitor (TNFi) and interleukin-17A inhibitor (IL-17Ai) in psoriatic arthritis (PsA) patients over a 4-month period after treatment initiation." (PMID 38474247, 2024). "Interestingly, while specific patterns of tender and swollen joint involvement are also observed in patients with psoriatic arthritis, manifestation of joint-specific effects does not appear to impact sensitivity to TNF inhibitor treatment." (PMID 37773189, 2023). "This study found three anti-TNF agents (adalimumab, infliximab, and etanercept) may be the preferred treatments for psoriatic arthritis for their superiority in achieving radiographic non-progression and reducing the total radiographic score." (PMID 36297574, 2022). "TNF-blocking agents, non-biological disease-modifying anti-rheumatic drugs (nbDMARDs) and non-steroidal anti-inflammatory drugs (NSAIDs) are commonly prescribed treatments in psoriatic arthritis." (PMID 25980667, 2015).
pulmonary fibrosis (428 papers, 1996 to 2026). Chronic progressive interstitial lung disorder characterized by the replacement of the lung tissue by connective tissue, leading to progressive dyspnea, respiratory failure, or right heart failure. "Nevertheless, in bleomycin-induced pulmonary fibrosis mice models, Axl deficiency leads to reduced IL-6 and TNFα expression and a decrease in M2-like macrophage differentiation in lung tissue." (PMID 41155824, 2025). "Other important mediators associated with lung fibrosis are legumain, osteopontin, IL-4, IL-6, IL-13, IL-17, TNF-α, Gal-1, Gal-3, PDGF, and FGFR-1." (PMID 38540252, 2024). "This constellation of findings demonstrates a paradigm wherein TNFα exerts pathogenic or protective roles in pulmonary fibrosis that depends on cell-specific and temporal cues that would benefit from further evaluation." (PMID 37849737, 2023). "An increased risk of pulmonary fibrosis in smokers is associated with genetic variations in genes encoding inflammatory mediators such as IL-1, TNF-α, and TGF-β." (PMID 37371940, 2023). "FZHY was effective in alleviating pulmonary fibrosis, whose action mechanism was associated with regulation of NF-κB/TNF-α signaling pathway in pro-inflammatory macrophages." (PMID 35548340, 2022). "What is supporting our findings is the observations of Tyagi and co-workers who reported that induction of macrophage-derived cytokines (TNF-α) and iNOS is associated with lung inflammation, and an increased risk of developing lung fibrosis and cancer." (PMID 35482242, 2022). "Earlier studies have documented the pro-inflammatory cytokines overexpression being associated with BLM induced lung fibrosis in animal models, including IL-1β, IL-6 and TNF-α." (PMID 35326173, 2022). "Lastly, it revealed that the action mechanism of FZHY against lung fibrosis was associated with NF-κB/TNF-α signaling in LPS-stimulated macrophage." (PMID 35548340, 2022). "Here we highlighted the effect of PL on several factors that contributed to lung fibrosis, including TNF, TGFb, CTGF or ET-1, but the precise underlying mechanism involved in this effect required further investigation." (PMID 36271442, 2022). "TNF-α produced by monocytes and macrophages are implicated in various pulmonary diseases, including pulmonary fibrosis." (PMID 34082837, 2021). "Taken together, TSSK4 upregulation in AT-II cells plays an important role in TNF-α-induced cellular apoptosis in vitro and AT-II loss in pulmonary fibrosis." (PMID 34645797, 2021). "In our study, similar to others, inflammatory factors including IL-6, TNFα, and related factors associated with pulmonary fibrosis were reduced, including TGF-β and IFN-γ." (PMID 34271988, 2021). "Inflammatory cytokines, including TNF-α and IL-1β, and immune cells, including neutrophils, are important causes of pulmonary fibrosis." (PMID 35115954, 2021). "In both (PQ) and (BLM)-induced pulmonary fibrosis models, the core pro-inflammatory cytokines underlying the pathogenicity of these conditions such as TNF-α, IL-6, IL-1β, and TGF-β are common with that of COVID-19 cases." (PMID 32574274, 2020). "MSCs modulate inflammation and alleviate pulmonary fibrosis caused by bleomycin (mouse model) through reducing lung fibrosis and preventing pulmonary malfunction by lowering secretion of TNF-α, IFN-γ, MCP-1 and IL-6 in lungs." (PMID 28286618, 2017). "This in turn causes an elevation in tumor necrosis factor alpha and in platelet- and fibroblast-derived growth factors, which are involved in vascular remodeling and lung fibrosis." (PMID 28659997, 2017). "On the other hand, it was previously demonstrated that lung-specific overexpression of TNF-α in mice was linked to a disease phenotype mirroring hallmark features of emphysema and pulmonary fibrosis." (PMID 26319657, 2015). "Among the several cytokines and chemokines that have been implicated in the pathogenesis of lung fibrosis, particular relevance has been given to IL-1 and TNF-α." (PMID 21477302, 2011).
pulmonary fibrosis (continued). "Bleomycin-induced lung fibrosis is associated with an increase in classical pro-inflammatory cytokines including TNF-α, IL-1β and IL-6 followed by a switch to pro-fibrotic markers (TGF-β1, fibronectin and pro-collagen-1)." (PMID 19956603, 2009). "Also, FPNI treatment prevented the upregulation of senescence markers that are well-known to be associated to lung fibrosis, such as TNF-α, Il6, Cdkn1a and Cdkn1b along with that of collagen isoforms Col1a1 and Col3a1." (PMID 38167804, 2024). "TNF-α increases the risk of pulmonary fibrosis by inducing the expression of IL-1, IL-6, and IL-8." (PMID 38515835, 2024). "Herein, we demonstrate in mouse models of lung damage following exposure to ionizing radiation that opaganib significantly improved long-term survival associated with reduced lung fibrosis, suppression of granulocyte infiltration, and reduced expression of IL-6 and TNFα at 180 days after radiation." (PMID 38396999, 2024). "In the early stage of the development of alveolar inflammation to pulmonary fibrosis, pro-inflammatory cytokines such as TNF-α, IL-1 and IL-6 increase, which play an important pathogenic role, and inflammatory cells also induce the production of matrix metalloproteinases." (PMID 37809072, 2023). "Moreover, the classical WNT/β-catenin pathway regulates inflammatory cytokines (TNF, IL-1, IL-6, IL-8, and IL-15), which play important roles in reducing lung inflammation and pulmonary fibrosis and are linked to the pathogenesis of BPD." (PMID 37180448, 2023). "Additionally, in various murine models, genetic and pharmacologic knockdown of TNFα and its receptor ameliorated chemically-induced lung fibrosis in a TGFβ dependent manner, suggesting a synergistic association between TNFα and TGFβ-mediated fibrosis." (PMID 37849737, 2023). "EDN1 has been implicated in pulmonary fibrosis and TNF-induced EndMT in cardiac fibrosis." (PMID 37841308, 2023). "The loss of AGER was caused by TGFB1 and TNF-alpha in the pulmonary fibrosis." (PMID 35185901, 2022). "In the past, anti-TNF-α therapy was viewed as a therapy that caused pulmonary fibrosis." (PMID 35163689, 2022). "Evidence from TNF-deficient mice, which are resistant to the development of silica-induced fibrosis, supports the idea that TNF-α plays a significant role in the development of pulmonary fibrosis." (PMID 36672608, 2022). "Many previous studies showed that lung tissues accumulate excessive amounts of the inflammatory cytokines, TNF-α and IL-6, which cause damage to lung cells, and might also induce the development of lung fibrosis." (PMID 32244835, 2020). "Our analyses identified significant enrichment of the protein targets of toxicity associated antibodies among functional pathways that have been associated with autoimmunity, such as TNF-α signaling, lung fibrosis, IL-1 and TLR signaling, and E. coli infection." (PMID 29606147, 2018). "Similarly, the collectin Pentraxin 3 can both be produced in lung endothelial cells in response to IL-1 or in lung fibroblasts in response to TNF-α and is associated with pulmonary fibrosis." (PMID 29100778, 2017). "Altered production of TNF-α, a pro-inflammatory cytokine has long been associated with various pathological conditions that affect the normal lung function, including radiation pneumonitis and lung fibrosis." (PMID 23468959, 2013). "First, as observed in the Sprague-Dawley rats, lung fibrosis is the consequence of a chronic and exaggerated inflammatory response associated with an overproduction of pro-inflammatory mediators also possessing pro-fibrotic activities such as TNF-α." (PMID 16212659, 2005). "Moreover, macrophage was the main resource of TNF-α in diseased lung, and we elucidated that FZHY could inhibit pro-inflammatory macrophage activation via NF-κB/TNF-α signaling pathway, which was closely associated with its efficacy on lung fibrosis." (PMID 35548340, 2022).